GSK3A (glycogen synthase kinase 3 alpha)
Diseases named in the same sentence as GSK3A in open-access papers (continued):
Sharing a sentence is not in itself a finding about the gene and the disease.
schizophrenia (6 papers, 2013 to 2025). A major psychotic disorder characterized by abnormalities in the perception or expression of reality. "This mouse line displayed a variety of schizophrenia-related abnormalities including hyperlocomotion, impaired pre-pulse inhibition/latent inhibition, deficient neurogenesis/neuron migration, enhanced dopamine function and dendritic spine deficits rescued by genetic inactivation of GSK3α." (PMID 32493513, 2020). "Our results address this issue to some extent, as we found evidence of the association of GSK3-α and GSK3-β with important clinical characteristics such as duration of schizophrenia." (PMID 41283305, 2025). "GSK3A is reported to be 80% lower in lymphocytes of patients with schizophrenia and is a regulatory enzyme of some neuronal proteins associated with schizophrenia abnormalities." (PMID 36993785, 2023). "Extensive studies have indicated decreased levels of GSK3α and GSK3β total protein in the lymphocytes of schizophrenia." (PMID 35062349, 2022). "In fact, it found a reduction in both cellular activities and protein levels of kinase FA/GSK3α in the lymphocytes of patients with schizophrenia, as compared to healthy controls." (PMID 24403877, 2013). "Thus, our data suggest that the dysregulation of the innate immune system by a TLR-2 deficiency may contribute to the development and/or pathophysiology of schizophrenia-like behaviors via Akt-GSK-3α/β signaling." (PMID 25687169, 2015). "Increased expression of intracellular GSK3-α and GSK3-β was detected in schizophrenia patients with a disease duration of more than 5 years (p = 0.019 and p = 0.018)." (PMID 41283305, 2025). "Moreover, the duration of the disease has a significant effect on the expression of GSK3-α and GSK3-β in schizophrenia patients." (PMID 41283305, 2025). "However, regarding the level of PI3K, AKT, mTOR, GSK3-α and GSK3-β in peripheral mononuclear cells (PMCs), the results are contradictory, possibly due to the heterogeneity of schizophrenia." (PMID 41283305, 2025).
tauopathies (6 papers, 2013 to 2025). "It was found that AS1842856 inhibits the GSK3α/β to suppress tauopathy by accelerating GSK3α/β exocytosis in cultured neural cells, whereas the in vivo studies of the inhibitor in the context of a neurological disorder are still lacking." (PMID 40260403, 2025). "To determine the localization of GSK3α in phospho-tau lesions, we co-immunostained post-mortem frontal cortices from patients with different tauopathies with anti-GSK3α and AT8." (PMID 40082954, 2025). "In translational terms, these data do not warrant the search for specific GSK3β inhibitors that spare GSK3α, as a therapeutic means for tauopathies in which GSK3 are thought to contribute." (PMID 23705847, 2013). "This was exacerbated by the pathological contribution of the onset of tauopathy, which were nevertheless still minor in the young GSK3α.KOxTau.P301L mice (age 1–2 months)." (PMID 23705847, 2013). "AS1842856 (AS) inhibits Tauopathy via promoting glycogen synthase kinase‐3α/β (GSK3α/β) exocytosis." (PMID 39287420, 2025). "Our proposed studies are serine 285 based phosphorylated tau targeting GSK3α, GSK-3β phosphokinases for AD and other tauopathies." (PMID 30893872, 2019). "Our results demonstrate that GSK3α is sequestered predominantly in neuronal inclusions across tauopathies, while it is mostly absent from glial lesions in PSP and CBD." (PMID 40082954, 2025).
diabetes (5 papers, 2012 to 2025). "We found that diabetes significantly increased ratio of p-AKT/AKT while decreased p-GSK3α/GSK3α; and AS-IV administration strikingly reversed effects of high glucose + high insulin on AKT and GSK3." (PMID 35341134, 2022). "A knockdown of GSK-3α in mice showed increased sensitivity towards insulin, suggesting the significant role of GSK-3α in glucose synthesis and as a therapeutic target for diabetes." (PMID 36497091, 2022). "We show here that reduced podocyte expression of GSK3α does not attenuate albuminuria in streptozotocin (STZ) diabetes or Adriamycin nephropathy models in mice." (PMID 31825015, 2019).
glioma (5 papers, 2013 to 2025). A benign or malignant brain and spinal cord tumor that arises from glial cells (astrocytes, oligodendrocytes, ependymal cells). "The PRKCG_S330 was specifically phosphorylated by GSK3A in the BrM/Glioma group, exhibiting unique activation in glioma samples." (PMID 39716938, 2025). "In contrast, NK-1R antagonists decrease both GSK-3α/β phosphorylation and glucose formation, counteracting the Warburg effect and inducing autophagy in glioma cells." (PMID 39941886, 2025). "In contrast, both NK-1R antagonists L-733,060 and L-732,138 counteract phosphorylation of GSK-3α/β in glioma cells." (PMID 39941886, 2025). "In summary, SP binds to the NK-1R of glioma cells and induces GSK-3α/β phosphorylation, glycogen degradation, and glucose formation." (PMID 39941886, 2025). "A recent report indicates that transfection with shRNA targeting GSK3α in U87 and A172 glioma cells upregulates GSK3β activity and results in increased levels of c-myc, pERK1/2 (Thr202/Thr204), and cyclin D1." (PMID 33339170, 2020). "The KD of GSK3α in U87 glioma cells promotes hnRNPA1 stability and mRNA synthesis to upregulate splice variant expression of the anti-apoptotic proteins BIN-1 and Mcl-1 with the parallel repression of RON, while in GSK3β inhibition, the opposite effect occurs." (PMID 33339170, 2020). "These antagonistic effects of GSK3α inhibition on glioma or neuroblastoma cell viability indicate the need to understand the cellular background to identify the inhibition of GSK3α as a therapeutic candidate against cancer of the nervous system." (PMID 33339170, 2020). "Consistently, down-regulation of GSK-3α and 3β by specific small interfering RNAs inhibited glioma cell invasion." (PMID 24312592, 2013). "Western blot analysis showed that EGF up-regulate phosphorylated GSK-3α and -3β levels in glioma cells upon mechanically scratching." (PMID 24312592, 2013). "Moreover, SP induces phosphorylation of GSK-3α/β (renders it inactive) in glioma cells." (PMID 39941886, 2025). "Consistently, the hyperphosphorylation of microtubule‐associated proteins (MAP2 and MAP1B) revealed the activation of CAMK2G, GSK3A, GSK3B, MAPK8, and MAP4K6, corresponding to the active MAPK signaling pathway in glioma." (PMID 39716938, 2025). "Taken together, these results suggested that GSK-3α and -3β were important for EGF-induced glioma cell invasion, in which GSK-3β was specifically regulated in an asymmetric way." (PMID 24312592, 2013). "Further, EGF regulated both GSK-3α and 3β, but only pSer9-GSK-3β was enriched at the leading edge of scratched glioma cells." (PMID 24312592, 2013). "Although both GSK-3α and 3β activities were regulated by serum and EGF, they likely played different roles in glioma cell migration." (PMID 24312592, 2013). "However, knock-down of GSK-3α and 3β by small interfering RNA eliminated the enhancement of cell invasion and over-expressing WT- or S9A-GSK-3β also suppressed glioma cell invasion induced by EGF." (PMID 24312592, 2013).
Anxiety (4 papers, 2009 to 2024). Intense feelings of nervousness, tension, or panic often arise in response to interpersonal stresses. "For instance, previous publications have shown that anxiety and depressive-like behaviors are associated with decreased brain levels of phosphorylated GSK3α/β." (PMID 28442992, 2017). "Studies in GSK-3β+/- mice have shown increased anxiety-associated behavior, which is similar to our findings in GSK-3α KO females." (PMID 19925672, 2009). "The combined data demonstrated interestingly distinct contributions of GSK3α to cognition and to anxiety-related behavior of mice." (PMID 23705847, 2013). "Notably, chronic administration of lithium, a mood stabilizer, restored the decreased phosphorylated GSK3α/β levels and rescued the depressive and anxiety-like behaviors in the Akt3 KO mice." (PMID 28442992, 2017). "In contrast, total lack of GSK3α caused significantly more defects and impairments in more tasks and for more parameters, with increased anxiety as extra noteworthy." (PMID 23705847, 2013). "The combined data demonstrated that neuronal GSK3α deficiency did not appreciably impinge on motor activity or on general behavior, nor induced anxiety in the AAC mice." (PMID 23705847, 2013). "The conclusion that neuronal deficit of GSK3α affected neither motor activity nor anxiety related behavior, was further confirmed in the dark–light paradigm." (PMID 23705847, 2013).
bipolar disorder (4 papers, 2014 to 2023). A disorder of the brain that causes unusual shifts in mood, energy, activity levels and the ability to carry out day-to-day tasks. "The aim was to search for consistent differences in GSK3α and GSK3β or of their phosphorylated forms in samples of peripheral blood from patients with unipolar and bipolar depression." (PMID 37807001, 2023). "LiCl is a commonly used drug for treatment of bipolar disorders with clinical relevance for more than 50 years and is known to inhibit the GSK-3α and β isoforms." (PMID 24767605, 2014). "Lithium, a common medication for bipolar disorder, inhibits GSK3 via Mg+ competition and increased Ser21 (GSK3α) or Ser9 (GSK3β) phosphorylation, leading to enhanced myoblast fusion and myogenic differentiation." (PMID 31671858, 2019).
colorectal adenoma (4 papers, 2019 to 2023). An adenoma that arises from the colon or rectum. "Our team also demonstrated that the downregulation of RAS homolog family member A (RHOA) and glycogen synthase kinase 3 alpha (GSK3A) expression in plasma may function as a diagnostic biomarker of colorectal adenoma using a target sequencing approach." (PMID 37446204, 2023). "GSK3A was detected in 22/39 (56.4%) normal plasma samples and 14/35 (40%) colorectal adenoma plasma samples with the median normalized expression of 8.0 (range: 0.0–57307.0) and 0.0 (range: 0.0–31591.0) CPM in normal and colorectal adenoma, respectively." (PMID 31506480, 2019). "The expression of GSK3A in colorectal adenoma was significantly lower than those in normal plasma samples (0.01-fold with adjusted P < 1 × 10−6)." (PMID 31506480, 2019). "Reduced GSK3A expression may be due to a dysfunctional immune response in colorectal adenoma, and inactivation of RHOA induces cancer cells to invade and de-differentiate through the Wnt signaling pathway." (PMID 37446204, 2023). "A loss of glycogen synthase kinase 3 alpha (GSK3A) and RAS homolog family member A (RHOA) expression in plasma may function as a biomarker of colorectal adenoma, a precancerous lesion of CRC." (PMID 35954375, 2022). "Reduced expression of GSK3A in colorectal adenoma may be the result of the dysfunction of immune response in tumorigenesis." (PMID 31506480, 2019). "Glycogen synthase kinase 3 alpha (GSK3A) and ras homolog family member A (RHOA) were two differential expressed genes (DEGs) detected between normal and colorectal adenoma based on the cut-off of fold change >2 and adjusted P value < 0.05." (PMID 31506480, 2019). "Using targeted mRNA sequencing, we found that GSK3A and RHOA had significant difference in gene expression in colorectal adenoma patients as compared with normal healthy subjects." (PMID 31506480, 2019). "Both GSK3A and RHOA showed a significantly lower expression in plasma samples from colorectal adenoma patients as compared to normal controls." (PMID 31506480, 2019). "Our preliminary results showed that GSK3A and RHOA were downregulated in the plasma of colorectal adenoma patients as compared to those of colonoscopy-proven normal subjects." (PMID 31506480, 2019). "Therefore, the AUC values of GSK3A and RHOA showed that the performance of those 2 genes are not good enough for the detection of colorectal adenoma as compared to FIT and faecal DNA test." (PMID 31506480, 2019).
fragile X syndrome (4 papers, 2021 to 2024). A genetic syndrome caused by mutations in the FMR1 gene which is responsible for the expression of the fragile X mental retardation 1 protein. "Selective inhibition of GSK3α corrected learning and memory deficits in the mouse model of Fragile X syndrome, the most prevalent inherited monogenetic cause of ID and autism." (PMID 39103699, 2024). "The use of BRD0705 to selectively inhibit GSK-3α (IC50 0.066 μM vs. 0.5 μM of α or β isoform respectively), revealed that inhibition of GSK-3α corrects excessive protein synthesis and ameliorates the susceptibility to audiogenic seizures in Fragile X syndrome (FXS) mice." (PMID 33572709, 2021). "On the other hand, selective inhibition of GSK-3α showed potential efficacy in treating Fragile X syndrome." (PMID 33572709, 2021).
heart failure (4 papers, 2017 to 2025). Inability of the heart to pump blood at an adequate rate to meet tissue metabolic requirements. "We note significant sex differences in the myocardial response by the autophagy protein p62, as well as GSK3α/β and ERK1/2, known mediators of cardiac dysfunction and heart failure." (PMID 37737732, 2023).
lymphoma (4 papers, 2017 to 2025). A malignant (clonal) proliferation of B- lymphocytes or T- lymphocytes which involves the lymph nodes, bone marrow and/or extranodal sites. "In this article, we show that inactivation of GSK-3α/β through siRNA or by SMIs during priming can substitute CD28 co-stimulation in the potentiation of cytotoxic CD8+ CTL function against the EL-4 lymphoma cells expressing OVA peptide." (PMID 29312284, 2017). "Indeed, lymphoma cells have shown an abundant expression of GSK3α/β with respect to normal B and T lymphocytes, both at the mRNA and protein levels." (PMID 40175588, 2025). "We have previously shown that the anti-lymphoma effects of elraglusib occur below the GSK3α/β IC50, cannot be replicated with other structurally distinct small molecule GSK3 inhibitors, and are unaffected by GSK3A/B knockdown, thereby questioning the role of GSK3 in its mechanism of action." (PMID 39470360, 2024). "Using a novel GSK3 inhibitor and through genetic knockout of GSK3α/β genes, GSK3 has been demonstrated to be functionally important for lymphoma cell proliferation and survival." (PMID 40175588, 2025). "Furthermore, as seen in the EL4 lymphoma model, a significant decrease in Pdcd1 gene expression was also seen in the Gsk3b cKO but not in Gsk3a cKO cells." (PMID 34142056, 2021).
neuroblastoma (4 papers, 2018 to 2025). Neuroblastoma (NB) is the most common solid, extracranial childhood tumor. "We have reported that treatment of neuroblastoma cell lines with AR-A014418 reduced the growth and associated with reduction in the level of GSK-3α phosphorylation at Tyr279 compared to GSK-3β phosphorylation at Tyr219." (PMID 29751783, 2018). "Treatment of neuroblastoma cells with CHIR99021 for 24h resulted in a significant decrease in the abundance of GSK3α and β isoforms in addition to an increase in their phosphorylation, consistent with a reduction in GSK3 activity." (PMID 40502782, 2025). "AR-A014418 represses neuroblastoma cell proliferation by similar GSK3α preferential inhibition related to increased apoptosis." (PMID 33339170, 2020). "For example, in a different approach using a cell-based alpha screen assay, the overexpression of 352 human kinases in the neuroblastoma cells SK-N-AS showed that GSK3α is the top kinase that preferentially promotes the phosphorylation of tau at Ser396/404, Thr231, Ser235, and Ser202." (PMID 33339170, 2020). "Moreover, in SH-SY5Y human neuroblastoma cells, transfection with siRNA against GSK3β, but not GSK3α, reduced the processing of APP to the intermediate C-99 fragment by reducing the BACE1 expression." (PMID 33339170, 2020). "Unlike some other neurons, the SH-SY5Y neuroblastoma cell line can store glycogen and expresses two GSK3 isoforms—GSK3α and GSK3β." (PMID 37512524, 2023).
Obesity (4 papers, 2013 to 2022). Accumulation of substantial excess body fat. "Furthermore, mice with a cardiac-specific heterozygous GSK3α deficiency subjected to high-fat diet-induced obesity demonstrated significant improvements in diastolic function, as seen by a lower deceleration time during Tissue Doppler analysis." (PMID 33041869, 2020). "Our findings provide encouragement to test the efficacy of this newly developed isoform-specific GSK-3α inhibitor against obesity, glucose clearance, and other metabolic conditions." (PMID 35159367, 2022). "Littermate controls and conditional GSK-3α KO mice were subjected to an HFD to induce obesity, and body weight and glucose clearances were observed at 4, 8, 12, and 16 weeks." (PMID 35159367, 2022). "In reference to the future perspective, the molecular basis for the differential effect of developing vs. established obesity on GSK-3α phosphorylation and β-catenin signaling is interesting, and needs further investigation." (PMID 32365965, 2020). "Interestingly, the effect of GSK-3 isoform deletion on HFD-induced obesity was completely the opposite: GSK-3α KOs were protected; however, GSK-3β KOs on chronic HFDs gained more weight, thereby losing the protective effect on glucose tolerance." (PMID 35159367, 2022). "GSK-3α KOs were protected against HFD-induced obesity and glucose intolerance." (PMID 35159367, 2022). "PPARα also contributes to the elevations in myocardial fatty acid uptake and subsequent lipotoxicity observed in obesity/T2D, which may be dependent on increased glycogen synthase kinase 3α (GSK3α) activity." (PMID 33041869, 2020). "Previously, in the developing obesity model, we saw a reduction in cardiac GSK-3α activity (decreased GSK-3α phosphorylation) in HF-fed CM-GSK-3β KO hearts leading to an impairment in GSK-3-β-catenin degradation pathway and cardiac dysfunction." (PMID 32365965, 2020). "We found that exposure to maternal obesity resulted in lower muscle GLUT-4 and Ser 9 phospho-GSK3α and higher muscle GSK3α abundance in lambs when compared to lambs conceived in normally nourished ewes." (PMID 24386400, 2013).
sarcopenia (4 papers, 2014 to 2022). Progressive decline in muscle mass due to aging which results in decreased functional capacity of muscles. "Intriguingly, mice with null mutation of GSK-3α showed premature death and acceleration of age-related pathologies such as vacuolar degeneration, large tubular aggregates, sarcomere disruption, and striking sarcopenia in cardiac and skeletal muscle." (PMID 25221510, 2014). "Glycogen synthase kinase-3 alpha (GSK3α) and Tyrosine-protein kinase (Fyn) are also involved in age-related alterations in sarcopenia by modulating autophagy." (PMID 36312227, 2022). "Therefore, it is expected that pharmacological inhibition (everolimus) of mTORC1 rescued the muscular disorder resembling sarcopenia in GSK-3α KO mice." (PMID 25221510, 2014). "In this context, the absence of GSK3α from cardiac tissue results in defective autophagy, leading to an impaired clearance of cellular debris, muscle contractile dysfunctions, and striking sarcopenia related to the premature death of GSK3α KO mice." (PMID 33339170, 2020).
Cognitive impairment (3 papers, 2009 to 2020). Abnormal cognition is characterized by deficits in thinking, reasoning, or remembering. "To examine whether the loss of GSK-3α was associated with cognitive deficits, we assessed memory and learning in GSK-3α KO mice in a Pavlovian fear conditioning paradigm as well as in a passive avoidance test." (PMID 19925672, 2009). "Compared with the model group, QKR significantly relieved the cognitive impairment, reduced the deposition of senile plaques, decreased the expression of GSK-3α and Aβ, and increased the expression of p-PI3K, p-Akt, and IDE." (PMID 32419798, 2020). "In NORT, the GSK3α.KO and GSK3α.KOxTau.P301L mice presented both with a minor cognitive impairment, and their decreased general activity and locomotion confirmed the open-field observations." (PMID 23705847, 2013).